TRPM4 (transient receptor potential cation channel subfamily M member 4)
Diseases named in the same sentence as TRPM4 in open-access papers (continued):
Sharing a sentence is not in itself a finding about the gene and the disease.
Progressive Symmetric Erythrokeratodermia (1 paper, 2021). "Currently, mutations in TRPM4 were identified in autosomal recessive Brugada syndrome and Progressive Symmetric Erythrokeratodermia (PSEK)." (PMID 33959666, 2021).
pulmonary hypertension (1 paper, 2021). Increased pressure within the pulmonary circulation due to lung or heart disorder. "TRPM4 expression in right ventricles was reduced in a rat model of pulmonary hypertension, and right ventricular hypertrophy was more severe when TRPM4 was absent (TRPM4 KO) compared with wild type animals." (PMID 35056097, 2021).
rectal cancer (1 paper, 2022). A primary or metastatic malignant neoplasm that affects the rectum. "In fact, germline variants of TRPM4, affecting the intestinal mucosal integrity, have been found in colon rectal cancer cells." (PMID 35804889, 2022).
renal carcinoma (1 paper, 2025). A carcinoma arising from the epithelium of the renal parenchyma or the renal pelvis. "In vitro functional experiments further supported the tumor-suppressive role of TRPM4 in renal carcinoma and its negative correlation with adverse tumor phenotypes." (PMID 41584840, 2025).
Respiratory insufficiency (1 paper, 2019). "Whereas inspiratory frequency increased following Trpm4 shRNA, we note that sigh rate decreased, and that may have further contributed to respiratory insufficiency by gradually diminishing the gas exchange surface area of the alveoli." (PMID 30789900, 2019).
schizophrenia (1 paper, 2024). A major psychotic disorder characterized by abnormalities in the perception or expression of reality. "Consequently, the significance of TRPM4 highlighted potential dysfunctions related to mitochondrial calcium homeostasis and glutamate excitotoxicity pathways, which may be implicated in the onset and progression of schizophrenia." (PMID 39202552, 2024).
sick sinus syndrome (1 paper, 2021). A constellation of signs and symptoms which may include syncope, fatigue, dizziness, and alternating periods of bradycardia and atrial tachycardia, which is caused by sinoatrial node dysfunction. "The two other patients with sick sinus syndrome were not tested for the TRPM4 variant, so we do not know if this variant is segregated with the phenotype of sinoatrial node dysfunction." (PMID 33797204, 2021).
skin inflammation (1 paper, 2022). "To investigate the role of TRPM4 in the physiology and pathophysiology of dermatitis and PSEK, we generated TRPM4 GoF mutant mice (I1029M) that have an equivalent mutation to human PSEK." (PMID 36341417, 2022). "Both GoF mice and wild-type (WT) littermates showed reduction of IMQ-induced dermatitis when treated with glibenclamide, a TRPM4 inhibitor." (PMID 36341417, 2022). "Clearly, other models of skin inflammation (such as tape-stripping) could be tested in the future to examine the specificity of TRPM4-mediated signaling." (PMID 36341417, 2022). "It is possible that TRPM4 GoF may mediate inflammasome-mediated signaling in the context of skin inflammation although this should be tested in future studies." (PMID 36341417, 2022).
cancer (66 papers, 2014 to 2026). A tumor composed of atypical neoplastic, often pleomorphic cells that invade other tissues. "Here we show two such factors-temperature and Ca2+-remodel the function and pharmacology of TRPM4, an ion channel implicated in cardiac conduction, immune regulation, cancer and intestinal-fluid homeostasis." (PMID 42265346, 2026). "Mutations and dysregulation of the transient receptor potential melastatin‐4 (TRPM4) ion channel have been associated with immune and cardiac diseases as well as cancer." (PMID 39821469, 2025). "Acetalax and bisacodyl kill cancer cells by causing oncosis following poisoning of the plasma membrane sodium transporter TRPM4 and represent a new therapeutic approach for TNBC." (PMID 39041239, 2024). "In cancer cells, TRPM4 upregulation is associated with cancer cell migration, proliferation, and invasion." (PMID 37892239, 2023). "Then the correlation between TRPs and hazard ratio (HR) was detected, and found that the TRPV1 was negatively correlated with cancer risk; TRPM1 and TRPM4 were positively correlated with cancer risk." (PMID 36072430, 2022). "In contrast, TRPM4 mRNA expression was higher in low-risk cancer tissues and cancer cells and with lower EMT status." (PMID 36230654, 2022). "Transient receptor potential melastatin 4 (TRPM4) ion channel malfunction or aberrant expression is implicated in many diseases, including different cancers and cardiovascular diseases." (PMID 34771564, 2021). "While some of these are under intense investigation (see also Section 4 on the functional role of TRPM4 in different types of cancer), future studies are needed to decipher the underlying mechanisms of the pathophysiology of TRPM4 in cancer." (PMID 33562811, 2021). "In contrast to cancer, mutations of TRPM4 have also been reported in other pathologies, such as cardiac conduction diseases." (PMID 33562811, 2021). "TRPM4 aberrant expression or malfunction have been linked to cardiovascular diseases, immune cell functions, and different types of cancer." (PMID 34771564, 2021). "Following overexpression in many tumor types and the multiple links to cancer hallmark functions, TRPM4 has been suggested to be a new potential anticancer drug target." (PMID 33562811, 2021). "Future studies will reveal if any of these TRPM4 blockers or the M4P antibody impact cancer hallmark functions of other types of cancer." (PMID 33562811, 2021). "In several types of cancer TRPM4 is overexpressed and contributes to cancer hallmark functions such as increased proliferation and migration and cell cycle shift." (PMID 33562811, 2021). "Currently, the underlying mechanism by which TRPM4 contributes to cancer hallmark functions is under investigation." (PMID 33562811, 2021). "In this paper, we review the emerging data about TRPM4′s involvement in cancer hallmark functions, as well as the correlation of TRPM4 expression with patient outcome." (PMID 33562811, 2021). "In contrast, TRPM4 is linked with an epithelial phenotype and its mRNA expression is higher in cancer biopsies and cancer cells with a lower EMT status." (PMID 34936030, 2021). "This is the first pharmacological approach showing that small molecule inhibitor, through inhibition of TRPM4 conductivity, alters cancer hallmark functions." (PMID 34771564, 2021). "TRPM4 contributes to several cancer hallmark functions, such as cell migration, proliferation, and the epithelial to mesenchymal transition (EMT)." (PMID 33562811, 2021). "The same was also reported in colorectal and pancreatic cancer, opening a door to future anti-cancer therapies based on the inhibition of TRPM4 in signaling pathways associated with EMT." (PMID 33291725, 2020). "Next, we investigated if cancer hallmark functions are directly dependent on TRPM4 ion channel conductivity." (PMID 31441200, 2019).
cancer (continued). "Further studies have shown that the expression of TRPM4 is upregulated in several cancers including breast, prostate and colorectal cancer, and that it contributes to cancer hallmark functions such as increased adhesion, migration, proliferation." (PMID 36081847, 2022). "Hence, TRPM4 is considered a potential diagnostic marker for cancer progression and a promising anticancer drug target candidate." (PMID 36230965, 2022). "Therefore, given the numerous associations with cancer hallmark functions, TRPM4 has been suggested to be a new potential anticancer drug target." (PMID 35804889, 2022). "TRPM4 is associated with proliferation, migration, and invasion of several cancer cells." (PMID 34257587, 2021). "Additionally, we provide an overview of TRPM4 in human cancer and discuss TRPM4 as a diagnostic marker and anticancer drug target." (PMID 33562811, 2021). "Recent studies suggested that TRPM4 may be implicated in regulating cancer cell migration and in the epithelial-to-mesenchymal transition." (PMID 33858332, 2021). "In addition, aside from CRC, aberrant expression of TRPM4 has been linked to cancers arising from prostate, liver, bladder, breast, and large B cells." (PMID 34771564, 2021). "TRPM4 channel activity is greatly enhanced by ATP depletion and increases in the intracellular Ca2+ level; both changes are associated with hypoxia, a condition commonly present in cancer cells." (PMID 35056097, 2021). "TRPM4 has been associated with cardiovascular and immune disorders, as well as cancer." (PMID 34771564, 2021). "Nevertheless, the fact that HCT116 T4KO cells show reduced proliferation and viability is important for the validation of novel TRPM4 inhibitors, as the inhibition of TRPM4 currents could potentially alter cellular functions and cancer hallmark functions in CRC cells." (PMID 34771564, 2021). "Given the upregulation of TRPM4 in various human cancers, our mechanistic insights into NC1 activation and specificity provide a framework for the potential development of cancer therapeutics targeting TRPM4-mediated necrosis." (PMID 41659621, 2026). "The observed relationship between TRPM4 expression and a better prognosis was supported by the analysis of clinical characteristics of cancer samples." (PMID 41226294, 2025). "Multiple Ca2+-handling proteins, including CACNA1D, CACNA2D1, TRPV4, TRPV1, TRPM4, MCU, and RyR1, exhibit cancer-associated overexpression or functional changes, correlating with poor prognosis and aggressive disease features." (PMID 41226294, 2025). "TRPM4 has been identified as a cancer driver gene in androgen‐independent PCa and has been associated with the risk of biochemical recurrence following radical prostatectomy." (PMID 39821469, 2025). "To investigate the prognostic significance of TRPM4 expression in 33 different types of cancer, we performed survival analysis using Cox proportional hazards modeling and assessed the correlation between TRPM4 expression and recurrence-free survival (RFS)." (PMID 41584840, 2025). "The relevance of TRPM4 as a drug target and biomarker for Acetalax and bisacodyl, which we discovered in a parallel study, highlights the potential of TRPM4 for developing additional drugs targeting the plasma membrane of cancer cells." (PMID 39932272, 2025). "In this study, we systematically elucidate the role of TRPM4 and sodium-overload–related cell death in ccRCC through integrated pan-cancer analyses, clinical datasets, and in vitro functional assays." (PMID 41584840, 2025). "Western blot analysis revealed a markedly reduced expression of TRPM4 in both cancer cell lines compared to normal controls." (PMID 41584840, 2025). "To explore the potential relevance of TRPM4 in cancer, we initially surveyed its mRNA expression across 33 different tumor types utilizing data from TCGA." (PMID 41584840, 2025). "Pan-cancer analysis revealed that TRPM4 was significantly downregulated in KIRC, and its high expression was associated with prolonged RFS." (PMID 41584840, 2025).
cancer (continued). "Similar results were observed for bisacodyl, which leads us to conclude that both Acetalax and bisacodyl poison TRPM4 to kill cancer cells." (PMID 39041239, 2024). "To elucidate the molecular target of Acetalax, we first correlated the sensitivity of 710 different cancer cell lines with gene expression and identified TRPM4 as a correlate." (PMID 39041239, 2024). "TRPM4 channel expression has been described in several cancers, including prostate, urinary bladder, cervical, colorectal, liver, and large B cell lymphoma." (PMID 37892239, 2023). "Although TRPM4 is impermeable to Ca2+, Na+ influx through TRPM4 reduces membrane potential and leads to a reduction in Ca2+ signaling in many different cells, including cancer cells." (PMID 36230965, 2022). "TRPM4 is upregulated in various cancers, and increased intracellular Ca2+ activates TRPM4, leading to Na+ ion influx." (PMID 36139707, 2022). "The TRPM4 channel also involved in regulating cancer cells to mesenchymal transition, migration and invasion." (PMID 35747124, 2022). "A TRPM4-mediated decrease in Ca2+ entry has been observed in various cellular systems, including immune, cancer, cardiac muscle, and dental pulp cells; however, other groups have found that TRPM4 mediates an increase in Ca2+ entry." (PMID 35681487, 2022). "TRP channels implicated in mechanotransduction mechanisms that regulate cancer cell migration, invasion and metastasis include, among others, TRPC1, TRPC5, TRPM2, TRPM7, TRPM4, TRPV2 and TRPV4." (PMID 36158191, 2022). "We found that TRP family genes are extensively involved in tumour progression and serve as risk factors for most tumours— especially TRPM2, TRPM4, and TRPM8 leading to poor prognosis of patients with cancer." (PMID 35493463, 2022). "Immunohistochemistry results showed that TRPM4 expression has strong correlation with cancer metastasis, which was validated by further migration and invasion assay and tumor metastasis in vivo." (PMID 36147460, 2022). "The aberrant expression or function of TRPM4 has been reported in various diseases, including different types of cancer." (PMID 35681487, 2022). "On the other hand, it is well-known that TRPM4 is involved in the growth and progression of several cancers." (PMID 35804889, 2022). "In cancers from prostate, liver, urinary bladder, cervix, colon, and large B cell, aberrant TRPM4 activity affects cancer cell growth and migration." (PMID 36380063, 2022). "Under these conditions, the Ca2+-induced increase in cell capacitance was reduced upon the down-regulation of TRPM4 with siRNA in all three cell lines, suggesting a more general role for TRPM4 in Ca2+-induced cancer cell exocytosis." (PMID 35681487, 2022). "TRPM4 is another TRPM channel subfamily member associated with cell migration and cancer metastasis." (PMID 36158191, 2022). "TRPM4 expression in the CCLE cancer cell lines was inversely correlated with the IC50 of acetalax in those cell lines (ρs = − 0.45, p-value < 2.2E-16), suggesting that cancer cell lines with higher TRPM4 expression are more sensitive to acetalax." (PMID 33858332, 2021). "In the case of the urinary bladder, the TRPM4 protein was only detected in urothelium, and its expression was equal in cancer and control groups, which raises questions about its role in that type of malignancy." (PMID 35056097, 2021). "Currently, the lack of potent and selective TRPM4 inhibitors limits further studies on TRPM4 in cancer disease models." (PMID 34771564, 2021). "They would allow to study the role of TRPM4 in disease models and to validate it as a potential target in therapies, including anti-cancer therapy." (PMID 34771564, 2021). "In contrast, increased levels of TRPM4 in cancer will stabilize β-catenin, which is mediated by alterations in the calcium/calmodulin/Akt1 pathway." (PMID 34360952, 2021).
cancer (continued). "In line herewith, our results showed increased TRPM4 mRNA expression in epithelial-like cancer cell phenotypes, represented by high cellular differentiation in low-grade tumors, and endometrioid histology." (PMID 34936030, 2021). "In the same study, TRPM4 protein was only detected in the epithelial cells of the bladder in both the cancer and control groups." (PMID 33562811, 2021). "Dysregulation of TRPM4 expression and functioning has been described in several diseases, including cancer." (PMID 34936030, 2021). "Future studies will reveal if the altered glycosylation or phosphorylation patterns of TRPM4 in cancer have pathophysiological implications." (PMID 33562811, 2021). "Most interestingly to us, TRPM4 protein levels are increased in a variety of tumor types compared to healthy tissue, where it contributes to important cancer features, such as increased proliferation and migration and cell cycle shift." (PMID 34680485, 2021). "In breast cancer, TRPM4 was shown to be upregulated in comparison to normal breast tissue, and its expression was correlated with higher cancer stage and lymph node status." (PMID 34771564, 2021). "In support of this notion, recent studies have highlighted the connection of TRPM4 expression with activation of the EMT in prostate and breast cancer cells, a process that has long been associated to cancer stemness." (PMID 34680485, 2021). "Aberrant TRPM4 expression has also been found in cancers from various tissues and organs such as prostate, liver, urinary bladder, cervix, colon, and large B cell." (PMID 34002002, 2021). "TRPM4 KD led to reduced migration but not proliferation of DU145 and PC3 cells, suggesting a role for TRPM4 in cancer cell migration and marking TRPM4 as an anticancer therapeutic target." (PMID 35056097, 2021). "Not only its expression pattern and links to different types of cancer but also the fact that TRPM4 is mostly expressed on the cell surface make TRPM4 an interesting target." (PMID 33562811, 2021). "TRPM4 also contributes to insulin secretion by pancreatic cells, immune cell activity, and plays a role in cancer." (PMID 35056097, 2021). "The first reports of TRPM4 in the context of cancer showed that the inhibition of this channel in HeLa cells generated a decrease in cell proliferation." (PMID 33291725, 2020). "For instance, TRPM4 is increased in cervical and prostate cancers, and its downregulation reduces cancer cell proliferation and migration." (PMID 32575381, 2020). "The altered expression profile of TRPM4 and TRPM5 has been associated with the etiology of several cancers." (PMID 32575381, 2020). "As such, future anti-cancer therapies based on the inhibition of TRPM4 in signaling pathways seem promising." (PMID 33291725, 2020). "Together with previous findings, the prominence of TRPM4 in CRC pathophysiology suggests a versatile role for TRPM4 in different types of cancer." (PMID 31441200, 2019). "Together with previous findings, our present data suggest that TRPM4 plays a versatile role in cancer cell proliferation, cell cycle, and invasion." (PMID 31441200, 2019). "On this basis, TRPM4 was identified as a cancer driver gene in androgen-insensitive prostate cancer through an increased migration." (PMID 29875336, 2018). "The ubiquitous expression pattern of TRPM4 implies a versatile role for TRPM4 in cancer cell migration." (PMID 26496025, 2015). "TRPM4 is overexpressed in several forms of cancer, and therefore could be considered a prospective prognostic marker and a promising anticancer target." (PMID 39932272, 2025). "TRPM4 mRNA is upregulated in several cancer entities but most prominently in PCa." (PMID 39821469, 2025). "On the other hand, β-catenin is a regulator of the expression of gap junction proteins, i.e., connexins, and, therefore, it can affect calcium signaling and modulate the membrane potentials of cancer cells, further adding to potential deregulations effectuated by TRPM4." (PMID 40332161, 2025).